FAP (fibroblast activation protein alpha)
Diseases named in the same sentence as FAP in open-access papers (continued):
Sharing a sentence is not in itself a finding about the gene and the disease.
tumor (continued). "The development of the selective and potent FAP inhibitor UAMC-1110 has led to synthetization of other promising radiolabelled FAP inhibitors tested in different tumour entities (FAPIs)." (PMID 33806468, 2021). "Subsequently, the importance of the CXCL12 signaling pathway in the regulation of tumor-infiltrating CD8 + T cell migration induced by FAP + CAFs, has been confirmed in several reports." (PMID 34635121, 2021). "A high expression level of LRP1 (ST) was significantly correlated with sex (p = 0.031), depth of tumor invasion (p = 0.024), high expression levels of αSMA (p < 0.001) and FAP (p = 0.001), and high numbers of infiltrating CD204+ macrophages (p = 0.001)." (PMID 33311557, 2021). "Future research regarding FAP in T1 disease should focus on this interaction, for example by assessing tumor infiltrating lymphocytes or CD8+ cells in tumour cells and the peritumoural stroma, and their correlation with FAP." (PMID 34525114, 2021). "Several reports have already demonstrated the efficacy of systemically depleting or targeting FAP+ cells in reducing tumor and stroma growth; however, serious side effects have been observed in these approaches, such as cachexia and anemia." (PMID 34064074, 2021). "FAP is a type II transmembrane serine protease expressed in activated tumor stroma and inflamed tissues during wound healing." (PMID 34858834, 2021). "For example, FAP+ CAFs in PDAC are also αSMA− during early stages of tumor formation, such as in PanINs (pancreatic intraepithelial neoplasia)." (PMID 33499238, 2021). "In its active dimeric form, FAP acts as an exo- and endopeptidase, influencing the proliferation, migration, and invasion of tumor cells." (PMID 33057927, 2021). "CAFs differ from normal fibroblasts in that they show a relatively higher tumor-specific expression of FAP, which is expressed in over 90% of human epithelial carcinomas but is almost absent in normal adult tissues." (PMID 35059319, 2021). "The tumor uptake of [177Lu]Lu-FAP-2286 in FAP-transfected HEK 293 xenografts was about 14%ID/g at 3 h post-injection and the retention remained high over 120 days (~9%ID/g)." (PMID 34681246, 2021). "Previous studies have reported the prognostic value of FAP expression in different tumors and its vital role in tumor invasion and metastasis." (PMID 34298868, 2021). "The antitumor activity revealed that 90% of the animal cohort treated with 60 MBq of [177Lu]Lu-FAP-2286 were tumor-free (tumor volume < 10 mm3) after 42 days." (PMID 34681246, 2021). "Among them, FAP is the most appealing therapeutic target owing to its selective expressions in tumor as well as its unique collagenase and gelatinase activities." (PMID 34670584, 2021). "FAPIs (fibroblast activation protein inhibitors) are a new class of radiotracers with highly promising results for detecting tumours that are characterized by a strong desmoplastic reaction and overexpressed FAP in their stroma." (PMID 34830575, 2021). "In this study, the established tracer FDG was compared to the FAPI tracer with regard to tracer uptake in cancer of Waldeyer’s tonsillar ring and correlated to the tumor size and FAP expression." (PMID 33057927, 2021). "Accordingly, injected anti-FAP BiTE and its infiltration to tumor microenvironment increase the intra-tumoral accumulation of T cells and cause cytotoxicity in cancer-associated fibroblasts." (PMID 34177890, 2021). "Especially immunohistochemical studies of HPV-positive and -negative tumors are necessary to further investigate the interaction between primary tumor/cervical lymph node metastases and CAFs as well as FAP." (PMID 33057927, 2021). "Ten FAP+ cell cultures from different patients were compared to the corresponding tumour tissue from which they were derived." (PMID 34282761, 2021). "The CAP-NPsupon FAP cleavage resulted in rapid and efficient release ofthe encapsulated drugs specifically at tumor sites." (PMID 34490078, 2021).
tumor (continued). "The level of FAP-α expression was significantly higher in the tumor stroma than in normal colonic mucosa samples." (PMID 33625532, 2021). "Previous reviews have summarized progress on the use of FAP in tumor diagnosis, however, many developments have been made since." (PMID 34490078, 2021). "Growing evidence has suggested that FAP is one of the immunosuppressive components in the TME that induces tumor-promoting inflammation." (PMID 34681246, 2021). "Another extensively studied protein with selective expression in several tumor types is FAP, a serine protease." (PMID 33669938, 2021). "The authors reported that the CAR-T cells showed specific cytotoxicity against FAP+ cells that resulted in inhibited tumor growth." (PMID 36284896, 2021). "Current FAP-targeting therapies mainly include diverse types of tumor vaccines and other immunotherapeutic approaches, such as adoptive T cell therapy, all of which can eliminate FAP + cells." (PMID 34635121, 2021). "It was also reported that depletion of FAP-expressing cells in Lewis lung carcinoma tumour models triggered acute hypoxic death of both tumour cells and stroma cells, that was regulated by interferon-γ (IFN-γ) and tumour-necrosis factor-α (TNF-α)." (PMID 33806468, 2021). "The cumulative results of which indicate that FAP expression influences tumor growth by impacting tumor cell proliferation and invasion, angiogenesis, epithelial-to-mesenchymal transition, immunosuppression, and drug resistance." (PMID 34490078, 2021). "An example is fibroblast activation protein α (FAPα), the overexpression of which is observed in the case of tumor progression." (PMID 34769123, 2021). "Such analysis revealed that the number of FAP+ CAFs was significantly reduced in tumours from nintedanib-treated mice compared with those from control mice." (PMID 33299131, 2021). "FAP overexpression on CAF of the tumor microenvironment has been confirmed in more than 90% of epithelial carcinomas, including malignancies of the breast, lung, colon and head and neck." (PMID 34050405, 2021). "FAP is able to operate the tumor cell behavior, therefore it can be used as an imaging tracer for many cancer types particularly colorectal, ovarian, pancreatic, and hepatocellular carcinomas which are identified by a strong desmoplastic reaction." (PMID 33864154, 2021). "As FAP and PD-L1 are abundantly expressed on tumor cells and within the tumor microenvironment, our approach has the potential to target a significant portion of human cancers using the same rAAV variant in combination with different bispecific antibodies." (PMID 34361120, 2021). "Numerous studies have indicated that FAP promotes tumor cell proliferation, migration, and invasion, which ultimately leads to tumor growth." (PMID 34490078, 2021). "Lately, it was suggested that FAP also contributes to immunosuppression in the tumor microenvironment (TME)." (PMID 33996747, 2021). "The tumours in which FAP was targeted were characterised by a reversion of the immunosuppressive environment and an increase in T-cell infiltration." (PMID 34298736, 2021). "The single arm, phase 2 ABACUS-trial with neo-adjuvant atezolizumab in patients with MIBC found that FAP expression remained high in relapsing tumours whereas a decrease was seen in responders, suggesting that FAP is linked to resistance to therapy." (PMID 34525114, 2021). "There is increasing understanding that expression of FAP promotes tumor occurrence, development, invasion, and metastasis, which worsens the patient’s condition and is associated with a poor prognosis." (PMID 34490078, 2021). "Radioimmunotherapy with 177Lu-labeled anti-FAP antibodies in melanoma-bearing mice delayed growth of established tumours and extended mouse survival, showing the potential for diagnostic and therapeutic use." (PMID 33806468, 2021). "The modified synthetic consensus FAP DNA vaccine synergized with other tumor antigen-specific vaccine therapies in tumor-bearing mice." (PMID 34305902, 2021).
tumor (continued). "FAP+ CAFs maintain tumour-permissive microenvironment by several mechanisms and play a well-documented role in the pathogenesis of epithelial cancers." (PMID 34282761, 2021). "Their presence was statistically significantly more frequent in tumours containing FAP+ mesenchymal cells (89%) compared to tumours containing HBVP (39%) or U87 alone (28%)." (PMID 34282761, 2021). "Several in vivo studies have shown that FAP inhibition leads to reduced tumor progression by favoring immune control." (PMID 34203869, 2021). "It was shown that FAP activation and its associated STAT3–CCL2 signaling in cancer-associated fibroblasts recruited immunosuppressive myeloid-derived suppressor cells and tumor-associated macrophages." (PMID 34209651, 2021). "By means of 68 Ga-labeling, positron-emission-tomography (PET) allowed imaging of FAP-expressing tumor lesions in animal models with high tumor-to-background ratios." (PMID 34417894, 2021). "Different immunotherapeutic agents have been developed to block FAP proteolytic activity, thus preventing tumor growth and proliferation." (PMID 33562504, 2021). "In comparison to FAPI-02, the ligands FAPI-04 and FAPI-46 have longer tumor retention time beyond 1 h p.i., which however would only be relevant in the perspective of FAP-targeted radionuclide therapy." (PMID 34137945, 2021). "DTR-mediated depletion of FAP-positive cells in an implanted model of pancreatic cancer decreased tumor burden and relieved immunosuppression." (PMID 34948209, 2021). "68Ga-FAPI is a radiolabelled agent targeting FAP, which is often present in tumor stroma, in addition to inflammatory tissue with prominent fibroblast proliferation as plasma cell-mediated sclerosing inflammation." (PMID 34181149, 2021). "Fibroblast-activation protein (FAP) is expressed on carcinoma-associated fibroblast (CAF), which is an important part of tumor extracellular matrix (ECM)." (PMID 34051801, 2021). "constructed a bivalent FAP-specific antibody through targeted selection and reported an increased affinity for tumor tissue and human-derived VL and VH chains." (PMID 34490078, 2021). "FAP molecules and FAP+ stromal cells play an important although probably context-dependent and tumor type-specific pathogenetic role in tumor progression." (PMID 34298822, 2021). "Targeting FAP has therefore the potential to increase tumor infiltration as well as anti-tumor activity by disrupting the extracellular matrix components." (PMID 33588928, 2021). "To preliminarily evaluate the potential of our nanoconstruct in vivo, we injected fluorescently labelled HFn-FAP into the tail vein of 4T1 tumor-bearing mice and monitored their biodistribution by fluorescence imaging at 1, 4, 24, and 48 h." (PMID 33562504, 2021). "STAT3-CCL2 signaling, which is activated by FAP, promoted tumor growth by enhancing the recruitment of MDSCs (CD11b+Gr1+) and macrophages, both of which express the CCR2 receptor, thus preventing antitumor IFNγ-T-cell immunity." (PMID 34771577, 2021). "Fibroblast activating protein (FAP) is known to be significantly upregulated in tissue remodeling, indicating tumor activity or fibrosis following the activation of fibroblasts." (PMID 33718446, 2021). "(A) MRI data from an individual rat implanted with FAP-expressing or control tumor cells (red and black arrowheads, respectively) in the dorsal striatum at bregma +2.2 mm." (PMID 34931988, 2021). "Of the investigated fibroblast markers, high expression of FAP and SPARC in tumor stroma and high expression of PDGFRB in MPM tumor cells were associated with shorter survival." (PMID 33955203, 2021). "All the so far acquired PET images utilizing several FAP-based radiolabeled inhibitors document a high tumor-to-background ratio in different tumor subtypes, rendering FAP-based radiotracers as potential pan-tumor imaging agents." (PMID 34681246, 2021).
tumor (continued). "Early phase trial data evaluating the FAP-specific humanized monoclonal antibody confirmed the safety and tolerability of the agent but with minimal evidence of tumor response." (PMID 34359823, 2021). "His studies focused on the tumor-promoting activity of the influx within sites of metastatic prostate cancer of tumor-infiltrating host-derived fibroblasts that have a highly increased plasma membrane expression of FAP." (PMID 34946547, 2021). "CAF are defined as being FAP+αSMA+ and are the most abundant stromal cell population within the tumor microenvironment." (PMID 34113615, 2021). "CTL activation was again found to be critical with this vaccine against FAP and is thought to be the mechanism through which the inhibition of tumor growth is mediated." (PMID 34200702, 2021). "Cancer-associated fibroblasts overexpress, in contrast to normal fibroblasts, the fibroblast activation protein (FAP), which contributes to tumor growth and metastatic spread in several tumor entities." (PMID 33207788, 2020). "In vivo studies have shown that FAP overexpression in breast and colonic xenograft models leads to more rapid development of subcutaneous tumors and enhanced tumor growth." (PMID 32733792, 2020). "In the first talk of the session, Raghu Kalluri highlighted the functional diversity of tumor-restraining (αSMA+) and tumor-promoting (FAP+) CAF subtypes in a mouse model of pancreatic ductal adenocarcinoma (PDAC)." (PMID 33088423, 2020). "Contrarily, a gradual increase in tumor fluorescence over time was peculiar in mice that received the FAP-IL or control LipQ." (PMID 32316521, 2020). "We prepared bispecific liposomes encapsulated with a high concentration of a self-quenching NIRF dye, DY-676-COOH and endowed them with targeting antibody fragments directed towards the universal tumor markers FAP and endoglin." (PMID 32316521, 2020). "The differential expression within the same tumor of canonical fibroblast cell markers such as FAP, podoplanin and αSMA clearly supports the simultaneous existence of phenotypically unique subpopulations." (PMID 33298926, 2020). "It has therefore remained unclear what proportion of tumor cells would be targeted by FAP‐directed immunotherapies." (PMID 33082953, 2020). "This is in keeping with its function as a protease capable of degrading extracellular matrix proteins, and our observation that clusters of tumor cells invading tumor‐adjacent brain tissue expressed FAP." (PMID 33082953, 2020). "Removing the CAFs expressing fibroblast activation protein (FAP), a protein that inhibits immune cell function, resulted in improved immune control over tumor growth and progression and uncovered the efficacy of immune modulating antibodies." (PMID 32466266, 2020). "Fibroblast activation protein α (FAP) plays an important role in tissue remodeling and helps tumor cells invade surrounding tissue." (PMID 32733792, 2020). "FAP+ cells can both promote tumor progression and present a barrier to immunotherapies through both their production of ECM and direct signaling pathways." (PMID 32402828, 2020). "Normal stroma in most organs contains a small number of quiescent or resting fibroblasts, whereas reactive tumor stroma is generally characterized by an increased number of activated fibroblasts that express αSMA, vimentin and FAP." (PMID 33260828, 2020). "A co-injection of cold FL excess blocked the tumor uptake which proofed the FAP-mediated binding and retention of the radiotracer." (PMID 33096754, 2020). "The results demonstrate highly fluorescence-quenched Bi-FAP/mEnd-IL and their selective binding to FAP and murine endoglin on cultured cells and in vivo in tumor models in mice." (PMID 32316521, 2020). "PET imaging with [68Ga]Ga-FAPI-02 demonstrated efficient tracer accumulation in FAP expressing fibrosarcoma tumor xenografts and its fast elimination from the blood." (PMID 33096754, 2020).
tumor (continued). "In this regard, the contribution of FAP+ stromal cells to GBM evasion of host anti-tumor immunity appears analogous to the well-documented roles of CAFs in enhancing immuno-suppression in solid cancers." (PMID 33308315, 2020). "In this respect, we prepared bispecific liposomes with 3 main peculiarities, for the simultaneous targeting of FAP and endoglin on the tumor stroma." (PMID 32316521, 2020). "Co-injection of excess of FL together with FL-L1-TubBH (competition) totally prevented the antitumor activity of the therapeutic conjugate, demonstrating that tumor killing was indeed FAP-mediated." (PMID 32483418, 2020). "Another promising strategy is the targeting of fibroblast activation protein-α (FAP) expressed on CAFs, to eliminate the tumor stroma and enabling infiltration into the tumor site." (PMID 32570906, 2020). "This substantiates the selectivity of the Bi-FAP/mEnd-IL for its designated targets, namely murine endoglin on tumor endothelium and murine FAP on the tumor myofibroblasts and pericytes within this tumor model." (PMID 32316521, 2020). "The combination of FAP expression at the tumour centre with sFAP levels (cut-off value = 61.03 ng/mL) showed low sensitivity (33.3%) but high specificity (95.6%)." (PMID 33207686, 2020). "Compared to the tumor center, FAP-positive cells were more frequently found at the invasive front (p = 0.03)." (PMID 32733792, 2020). "Hepatic CAFs commonly marked with α-SMA and FAP are widely distributed in tumor septum, fibrous capsule, and hepatic blood sinusoids." (PMID 33292459, 2020). "Taking all this evidence into account, we decided to analyze FAP expression individually and in combination with these markers in the tumor center and at the infiltrating front of primary AdCs." (PMID 32428869, 2020). "Recent work from our lab has demonstrated the existence of phenotypically and functionally divergent populations of tumor mesenchymal cells, unveiling a previously unappreciated dichotomy of the FAP+ stromal cell compartment." (PMID 33298926, 2020). "Injection of FAP-targeted 99mTc into tumor-bearing mice enabled facile detection of tumor xenografts with little off-target uptake." (PMID 32483418, 2020). "The authors demonstrated that the absorption of the complexes was FAP-dependent and that tumor angiogenesis, as well as tumor cell invasion and migration, was significantly inhibited in vitro." (PMID 32751200, 2020). "FAP-α expressing cells are a significant immunosuppressive component that can result in the hypoxic necrosis of tumor and stroma cells through a process involving IFN-γ and TNF-α." (PMID 33634030, 2020). "The enrichment for CMS4 tumors among tumors with high FAP expression suggests a more invasive tumor phenotype, which agrees with our findings from the TMA." (PMID 32733792, 2020). "Of all the approaches used, analysis of dissociated tumor tissue by flow cytometry revealed the lowest levels of FAP on tumor cells, with only a small fraction showing detectable expression." (PMID 33082953, 2020). "FL-L3-99mTc was observed to accumulate in MDA-MB231 solid tumors (2.23% ID/g) and a co-injection of excess of FL was seen to block this tumor uptake (0.13 ± 0.06 %ID/g), suggesting that tumor retention was FAP-mediated." (PMID 32483418, 2020). "FAP represents a promising biomarker that can be exploited to target a variety of pathological conditions and possibly the tumor microenvironment using PET." (PMID 32806623, 2020). "FAP expression at the centre and at the edge of pT2 tumours significantly increased with respect to pT1 ones." (PMID 33207686, 2020). "Since human and mouse FAP protein have a high amino acid sequence homology and antibody cross-reactivity, the human FAP’scFv on the liposomal surface would react with murine fibroblasts on the tumor stroma of xenografted human cancer models in mice." (PMID 32316521, 2020).